CD74 (CD74 molecule)
Diseases named in the same sentence as CD74 in open-access papers (continued):
Sharing a sentence is not in itself a finding about the gene and the disease.
tumor (continued). "The interaction between MIF and CD74 can enhance the stability and biological activity of MIF, influencing tumor development and progression." (PMID 38277205, 2024). "Increased levels of tumor-expressing and circulating MIF, DDT, and CD74 have been detected in early- and late-stage cervical cancer and have been linked to lymphatic metastasis and up-regulation of E-cadherin and vimentin." (PMID 38732068, 2024). "In this process, the absence of CAF_CCL21 also impairs complement-dependent CR2 activation of B_CD74, while the dysfunction of B_CD74 weakens CD6-dependent activation of CD8+ T cells, thereby attenuating their involvement in anti-tumor immunity." (PMID 38505619, 2024). "In support of this finding, immunoblotting of tumor lysates from TNBC-related patient-derived xenograft (PDXs), showed that in TNBC setting, elevated CD74 expression positively correlates with the activation of AKT signaling pathway." (PMID 39056676, 2024). "Through transcriptional trajectory analysis, we discovered a specific cluster of tumour cells in LSCC with COPD that exhibited high expression levels of MHC II‐related genes, including CD74, HLA‐DRA and HLA‐DMA." (PMID 39113235, 2024). "Some clusters expressed a combination of markers associated with tumor proliferation and invasiveness, such as CD44, S100A4, CD74 and MMP-9 (Tumor 7, 29.1%, n=8; range 0.7-81.5% per PDAC)." (PMID 39575252, 2024). "Single-cell CD74 expression data were obtained from TISCH, demonstrating that CD74 was mostly found in both M1 macrophages and tumor cells in most cancers." (PMID 38582956, 2024). "Their crosstalk subsequently shaped the tumor microenvironment of HCC, possibly through the CD74-MIF axis." (PMID 39118044, 2024). "In lung squamous cell carcinoma, tumor MIF expression correlates with lymph node metastasis and worse disease-free survival, and in mesothelioma, CD74 tumor enrichment independently predicts improved survival." (PMID 38732068, 2024). "CD74 is highly expressed in the tumor tissue of diethylnitrosamine/CCl4-treated C57BL/6 mice, and CD74 in tumor cells exerts pro-carcinogenic effects by triggering fibrogenesis during HCC development." (PMID 39118044, 2024). "It has been reported that CD74-MIF signaling pathway regulates PD-L1 expression and promotes tumor cells escape from immune surveillance." (PMID 38280003, 2024). "The interactions where non-tumor cells influenced tumor cells included NAMPT → INSR, MIF → CD74 and CXCR4, GRN → SORT1, and CD99 → CD99." (PMID 39095793, 2024). "To further validate the positive relationship between the CD74‐202/CD74‐201 ratio and the enrichment of CD8+CXCL13+ Tex cells and C1QC+ TAMs, we performed the same SiT sequencing and analysis pipeline on 13 tumor samples extracted from 13 ESCC patients." (PMID 39312471, 2024). "Four tumor-related genes (NR4A3, CD74, PPP1R3C, and ANKRD1) with high differential expression were selected, and the GeneMANIA database was used to generate a protein–protein interaction (PPI) network diagram." (PMID 39474111, 2024). "Analyzing the tumor-immune cell interaction of ACP in tumor tissues revealed signals such as NXA1-FRP152 and MIF-CD44/CD74,53,54 which inhibited leukocyte migration, between tumor cells and macrophages in calcification." (PMID 39483146, 2024). "In the context of signal regulation by TEXs in tumor cells, our findings pointed to MIF-(CD74+CD44) as a significantly more potent regulatory signal, playing a pivotal role in driving malignant tumors." (PMID 38683136, 2024). "In past studies, multiple prognostic models have been constructed because of the differential expression of CD74 or TSPAN7 between tumor and normal tissues." (PMID 36911401, 2023). "In contrast, we found that inflammatory interactions between tumor cells or Scissor+ tumor cells and myeloid cells were significant increased, such as APP‐CD74, and MIF‐(CD74 + CD44)." (PMID 37021816, 2023).
tumor (continued). "Our results confirmed the spatial proximity of multiple sets of ligands and receptors, such as ANXA1‐FPR1, APP‐CD74, MIF‐(CD74 + CD44), and CD99‐CD99, and they basically correspond to the location of tumor cells, myeloid cells, and T cells, respectively." (PMID 37021816, 2023). "However, the biological function(s) of CD74 in tumor cells is largely unknown." (PMID 37081824, 2023). "The six HCC TAN clusters; MMP8+, APOA2+, CD74+, IFIT1+, SPP1+ and CCL4+ can be characterised by predicted function and role in tumour development." (PMID 37534829, 2023). "Mechanistically, MIF independently interacts with CD74 in a hetero-complex with CD44, CXCR2, CXCR4, and ACKR3 to initiate downstream MAPK and PI3K pathways, all of which influence tumor initiation, growth, and metastatic dissemination." (PMID 38065972, 2023). "In patient-matched tumor and peripheral blood, we verified gene expression by examining concordant protein expression for each pathway category: TMSB10 (cell motility), CD74 (immune evasion) and GPX1 (metabolism)." (PMID 38106024, 2023). "After identifying all hybrid cells within a tissue section or peripheral blood slide, we quantified the average fluorescent intensity of each phenotypic marker TMSB10, CD74 and GPX1 across all hybrid and tumor cells from each patient." (PMID 38106024, 2023). "The S100A12+, ISG15+ and TXNIP+ subtypes are found in peripheral blood, the ELL2+ and PTGS2+ mainly in adjacent liver and the MMP8+, APOA2+, CD74+, IFIT1+, SPP1+ and CCL4+ predominantly located in the tumour." (PMID 37534829, 2023). "This revealed several strong putative interactions between GBM tumor cell ligands and macrophage receptors that were conserved over the different co‐cultures, including APP:CD74, CD99:PILRA, PTN:ALK, and CLU:TREM2." (PMID 37791581, 2023). "We further verify that expression of three genes identified from our scRNA-seq analyses, thymosin beta 10 (TMSB10), CD74 and GPX1, are expressed at the protein level in hybrid cells within patient-matched primary tumor and peripheral blood." (PMID 38106024, 2023). "MIF-(CD74+CXCR4) and MIF-(CD74+CC44) interactions happened in dendritic cells, M1 macrophage, M2 macrophage, monocyte, and plasma cells both in tumor and normal tissues." (PMID 37335089, 2023). "Through the PI3K/AKT/EGR-1 pathway, CD74 enhances tumor invasion and promotes neuroplasticity by increasing GDNF secretion, thereby facilitating tumor invasion." (PMID 38099290, 2023). "CD74 and MHC-II genes, also components of the MPR signature, are required for tumor antigen presentation." (PMID 36869384, 2023). "CD74 and TSPAN7 expression was negatively correlated with tumor purity while positively correlated with the level of multiple immune cells." (PMID 36911401, 2023). "Blocking the CD74-MIF axis potentiates CD8+ T cell infiltration and drives pro-inflammatory M1 conversion of macrophages in the tumor microenvironment." (PMID 36494694, 2022). "Several therapeutic strategies under development use antibodies to block MIF or CD74 and thus prevent MIF signaling in different tumor types." (PMID 36352420, 2022). "The differential analysis also confirmed the high expression of CD74, HLA-DRA, C7, CCL12, and CCR3 in CAFs from P-LN but lower expression of VIM, APOD, MMP11, TAGLN, and CDKN2A compared with that in the primary tumor." (PMID 36569924, 2022). "Expression profiles of MIF, CXCL12, and the receptors CXCR4, CXCR2, CXCR7, CD74, and CD44 were first analyzed using an RNA sequencing (RNA-seq) dataset (GSE62564) of 498 primary NB tumor samples." (PMID 35715791, 2022). "In particular, we discovered that macrophage migration inhibitory factor (MIF), which interacts with CD74+CXCR4+ and CD74+CD44+, was specifically expressed in tumor samples." (PMID 35967424, 2022).
tumor (continued). "Specifically, by expressing MHC II, CD74, CD80/CD86 and CD11c, they function as tumor antigen-presenting cells, and activate T cells, leading to tumor cell death and clearance." (PMID 36411434, 2022). "Based on the results of CellPhoneDB, the CD74-MIF/COPA/APP interactions between B cells, dendritic cells, macrophages and epithelial cells were identified in the residual tumor compared with tumor bed." (PMID 35784460, 2022). "MIF interacts with its receptor CD74 to activate the IFNγ-JAK-STAT pathway, resulting in significant upregulation of PD-L1 in melanoma cells, which aids in tumor cell escape from the immune response and maintenance of immunosuppressive TME." (PMID 35842634, 2022). "Specific to MIF signaling in tumor tissue, CellChat identified ligand MIF and its multi-subunit receptor CD74+CXCR4 as the most significant signaling, contributing to the communication from CD4+ T cells to CD8+ T2 and CD8+ T3 cells." (PMID 35812372, 2022). "Multiple genes (HLA-DRA, HLA-DRB1, OAS1, and CD74) differentially expressed in NSCLC B cells, peripheral blood lymphocytes, and tumor T cells had concordant prognostic indications at the mRNA and protein expression levels." (PMID 35804895, 2022). "Among the identified DE genes in NSCLC PBL T cells and tumor T cell clusters, HLA-DRA, HLA-DRB1, OAS1, and CD74 had concordant prognostic indications at the mRNA and protein expression levels in bulk NSCLC tumors with resectable disease." (PMID 35804895, 2022). "CD24, CD74, PGK1 showed significantly higher expression in tumour tissue compared with tumour adjacent normal tissue, while STX11 and NFKBIA showed the opposite trend (p < .001 for all)." (PMID 34187256, 2021). "CD74, GIMAP4, HCST, and HLA-DMA not only showed good clinical phenotype correlation but also correlated with M2 type macrophages, tumor purity, and immune score." (PMID 33854546, 2021). "A striking feature of KRAS KO tumor cells was a significant 2–10-fold increase in MHC gene expression (H2d1, H2k1, B2m, and H2-aa, H2-ab1, CD74) over KRAS intact controls." (PMID 33674596, 2021). "Some of these pairs have been reported to have broad functions; for example, CD74-MIF is involved in many biological processes in cardiac function, tumor formation, and inflammation modulation." (PMID 34546071, 2021). "In addition, tumor-bearing SAMs displayed a high expression of complement C1q A chain and B chain (C1qa and C1qb) and triggering receptor expressed on myeloid cells 2 (Trem2), and a low expression of the major histocompatibility complexes (Cd74, H2-D1, H2-Aa, and H2-Eb1) compared with control SAMs." (PMID 33782087, 2021). "While CD74 has been further described as one of the most up-regulated molecules in human glioblastomas, it was shown that the expression was restricted to glioma-associated macrophages and was absent in tumor cells, with the latter strongly expressing its ligand MIF." (PMID 34571885, 2021). "In seeking to target the interaction of MIF and CD74 on MDSCs we identified Ibudilast as an agent of interest, and were able to treat mice to reduce CD74 expression and increase CD8 T cells in the tumor." (PMID 32625208, 2020). "Taken together, these data reveal that CD74/MIF inhibition via Ibudilast can reduce MDSCs in vivo and increase immune activation in the tumor microenvironment." (PMID 32625208, 2020). "Many of these complexes are under populated by HLA-DRs, leaving CD74 molecules on the surface of the cell that can bind to MIF and function as a transcription factor to promote tumor cell survival." (PMID 32934776, 2020). "Fusion partners that participate in ROS1 rearrangements include CD74, SLC34A2, SDC4 in addition to GOPC/FIG, which was observed in this patient's tumor." (PMID 30719217, 2019).
tumor (continued). "In particular, inhibition of (IFN)-γ secretion in microglia seems to play a crucial role in the prooncogenic role of MIF, as blockade of MIF/CD74 interaction promotes IFN-γ release and amplifies tumor death." (PMID 29707160, 2018). "Recently, it has been shown that CD74 and CD44 promote actin polymerization via RHOA-mediated CFL1 phosphorylation; it is thought that this interaction contributes to tumour metastasis." (PMID 29190904, 2017). "Increased expression of MHC class II genes CD74, HLA-DMB, and HLA-DQA1 indicate higher tumour antigen processing by the antigen presenting cells in clusters III and IV." (PMID 29050337, 2017). "A previous study that performed immunohistochemical analysis with anti-CD74 (HLA class II histocompatibility antigen gamma chain) and anti-HLA-DPB1 in TNBC tumor specimens revealed that all five examined specimens had CD74 protein expression in tumor cells." (PMID 28817603, 2017). "Tumor cell expression of MHC II and CD74 were evaluated by flow cytometry after 3 weeks of treatment." (PMID 28498806, 2017). "CD74 is an important component in the functional presentation of MHCII restricted antigens, a key factor in anti-tumor immunity." (PMID 27058619, 2017). "Our group has recently shown that the majority of malignant mesothelial tumor cells express MIF and its receptor CD74, with a homogenous distribution between the different histological subtypes." (PMID 26883190, 2016). "Recently, we have shown that the majority of the malignant mesothelial tumor cells expressed MIF and its receptor CD74, with a homogenous distribution between the different histotypes." (PMID 26883190, 2016). "In this study, our results show that CD74 and CD44 coordinately promote actin polymerization via RHOA-mediated CFL1 phosphorylation, enhancing tumor cell metastasis." (PMID 27626171, 2016). "Decreasing MIF or CD74 expression in H28 and H2052 MPM cells reduced multiplication rate of the tumor cells due to a reduction in proliferation and an increase in apoptosis." (PMID 26883190, 2016). "Tautomerase-null MIF retains its ability to bind CD74 and CSN5 and the tumor forming capacity, indicating that the tautomerase activity of MIF is dispensable for its transformational function." (PMID 26352431, 2015). "The main findings from our studies are that tumour-derived CatS can transcriptionally regulate the pro-inflammatory chemokine CCL2, in a CD74-dependent manner and influence the tumour microenvironment, by altering cellular recruitment of macrophages." (PMID 26358505, 2015). "DC101 significantly inhibited the CPA-stimulated tumor recruitment of macrophages (CD68 marker), dendritic cells (CD74 marker), and NK cells (NKp46 marker) and their cytotoxic effectors, perforin, granzymes, and lysozymes." (PMID 24965046, 2014). "Consistent with the microarray transcript data, immunohistochemical staining confirmed increased expression of HLA-DR, CD74, and TAP2 proteins in the tumor epithelium of the low-volume ascites group." (PMID 24982872, 2014). "B cells from CLL patients have higher cell surface levels of CD74 than do normal B cells, and it was shown that the activation of CD74 by MIF in CLL cells activates NF-κB and induces secretion of IL-8, which promotes cell survival and tumor progression." (PMID 25304249, 2014). "Along with traditional markers such as FABP5, epidermal growth factor receptor, E-cadherin, CD74, and CD24, newly published biomarkers for the staining of HNSCC primary tumor biopsies include IL13Rα2, CD44v6, and the stem cell marker CD133." (PMID 20175927, 2010). "Although tumor 01-762 was the only tumor sample analyzed by this approach and the prevalence of the altered ratio among all the tumor samples therefore remains unknown, it is indicative of transcriptional up-regulation of the novel Cd74 isoform by proviral insertion in this specific tumor." (PMID 20416035, 2010).
tumor (continued). "Five potential novel target genes (FABP5, CD24, CD44, CD74, and HSP27) were identified, which were highly expressed in HNSCC tumor samples and tissue arrays." (PMID 19602232, 2009). "Autocrine MIF promoted tumour cell proliferation, as indicated by blockade of MIF or CD74 in MDA-MB-231 and MDA-MB-468, and MDA-MB-231 invasiveness was enhanced by exogenous MIF." (PMID 19602265, 2009). "Similarly, Shvefel and colleagues found Cd74 to be increased across several time points in the rejected clones and in response to MIF KO tumor clones in their scRNA‐seq analysis." (PMID 40131169, 2025). "Additionally, MIF signaling through the CD74/CD44 receptor complex activates the ERK MAP kinase pathway, further promoting tumor cell proliferation." (PMID 41159021, 2025). "ST data further confirmed the spatial co-localization of tumor and immune cells, as well as the expression of co-inhibitory ligand–receptor pairs, such as SPP1/CD44 and MIF/CD74, highlighting the mechanism by which tumor cells promote immune escape through the expression of co-inhibitory factors." (PMID 40867511, 2025). "Unlike anti-tumor neutrophils, pro-tumor neutrophils express low HLA-DR and CD74; rather, they exhibit Programmed death-ligand 1 (PDL-1), CD66b, and CD15, which contribute to immunosuppression in the tumor microenvironment." (PMID 41009604, 2025). "Differentiation between SSR4+ and SSR4- cells suggests that SSR4 might regulate the interactions between ESCC tumor plasma cells and TME, possibly by modulating the MIF/CD74/CXCR4 axis." (PMID 40066443, 2025). "It is through this continuous antigen presentation and T‐cell activation that CD74+ B cells are able to maintain the TLS as a mature, functional structure, thereby effectively initiating and continuously driving antitumor immunity within the tumor." (PMID 41111459, 2025). "Furthermore, we found that, compared to tumor tissues, T cell subsets in normal tissues were more regulated by iCAFs and apCAFs through pathways such as CXCL12-CXCR4 and MIF-(CD74+CXCR4)." (PMID 40740774, 2025). "Heterogeneous vascular endothelial cellscan secrete molecules such as MIF and APP, which act on macrophagesurface molecules or complexes such as CD74 and CD44, inhibiting macrophagepolarization toward the antitumor M1 phenotype and promoting polarizationtoward the pro-tumor M2 phenotype." (PMID 40834268, 2025). "Co-expression of MIF and CD74, detected using factor VII staining, correlated with elevated levels of angiogenic CXC chemokines and greater tumor vascularity, which reinforces MIF’s role in promoting tumor angiogenesis." (PMID 41159021, 2025). "However, both CD74 and CXCR4 were highly expressed in the infiltrating immune cells within the tumor tissues." (PMID 40018995, 2025). "Across both tumor clusters, MDK–(ITGA4+ITGB1) and MIF–(CD74+CXCR4) emerged as prominent axes." (PMID 40948762, 2025). "Moreover, MIF, through binding with CD74 and CXCR4, facilitates tumor cell migration and invasion and regulates the immunosuppressive state in the tumor microenvironment." (PMID 40110199, 2025). "On the other hand, we found that after apCAF (Fib_CD74+) lost its MHC II-mediated antigen presentation ability in the tumor microenvironment, it no longer directly activated T cells." (PMID 40948762, 2025). "CD74, a non-polymorphic type II transmembrane glycoprotein present on the surface of immune and tumor cells, activates ERK, MAPK, and NF-κB signaling upon interaction with MIF and its coreceptor CD44." (PMID 39028303, 2024). "The enrichment of CD74 and CD44 receptors in the tumor tissue suggests the potential interaction between FABP6+ tumor cells and Treg cells, which may contribute to immunosuppression and tumor development." (PMID 38277205, 2024). "Furthermore, the expressions of CD74 and CXCR4 were higher in GrB+ B cells from the tumor group compared to the control group." (PMID 38386050, 2024).